TSLP (thymic stromal lymphopoietin)
Diseases named in the same sentence as TSLP in open-access papers (continued):
Sharing a sentence is not in itself a finding about the gene and the disease.
asthma (continued). "Because of the increase in expression of TSLP, compared with non-smoking asthma patients, smoking asthma patients have significantly increased airway inflammation, and persistent airway inflammation can aggravate airway remodeling through repeated airway epithelial damage and repair." (PMID 36741543, 2023). "Although a number of proinflammatory mediators may contribute to asthma per se, and may even be derived from fibroblasts, in pilot studies using a multiplex assay, we found IL-6, IL-8, CCL5 and TSLP to be particularly expressed, and importantly changed by TNFα treatment." (PMID 36760534, 2023). "We present the case of a 74-year-old woman with severe asthma, ECRS, and secretory otitis media with possible eosinophilic otitis media, who experienced significant improvement in both conditions after treatment with tezepelumab, an anti-thymic stromal lymphopoietin (TSLP) antibody." (PMID 38022039, 2023). "Therefore, we hypothesized that CpG-ODN administration suppresses the TSLP-DC pathway by downregulating the IL-33/ST2, thereby alleviating the Th2/Th17 type inflammatory response to smoke-related asthma." (PMID 36834541, 2023). "Among them, thymic stromal lymphopoietin (TSLP) is a novel interleukin (IL)-7-like cytokine and could initiate type 2 inflammatory response by TSLPR heterocomplex, which is composed of the IL-7Rα chain and TSLPR chain, in asthma airway." (PMID 35351157, 2022). "In this light, it seems interesting that anti-TSLP monoclonal antibody therapy reduced exacerbations in patients with severe asthma with non-T2 inflammation, and thus TSLP may play a role in patients with little or no T2 inflammation." (PMID 35572064, 2022). "However, treatment with probiotics (2.1 ± 0.5 ng/ml) and prebiotics (2.6 ± 0.2 ng/ml) reduced TSLP level in the BALF as compared to asthma control animals, but these were not statistically significant (p > 0.05)." (PMID 35296330, 2022). "The anti-TSLP mab, tezepelumab, has been approved in severe and uncontrolled asthma with significant reductions of exacerbations and improvements in lung function, symptom control and health-related quality of life, and is currently in phase III trials for asthma." (PMID 35743678, 2022). "A further contribution to the pathobiology of T2-high asthma is provided by other cellular elements releasing IL-4 such as T follicular helper cells (Tfh), whose differentiation in lung-draining lymph nodes is dependent on OX40L-positive dendritic cells activated by TSLP." (PMID 33922072, 2021). "The production and release of epithelial cytokines, including IL-33, IL-25, and TSLP, lead to the recruitment and activation of ILC2, which secretes mediators, such as IL-5 and IL-13, that augment allergic inflammation in the pathogenesis of virus-induced asthma exacerbation." (PMID 35008429, 2021). "Interestingly, TSLP expression in moDCs from triple co-culture correlated positively with IL12p40, IL-6, and TNF-α in asthma, whereas in COPD with CHI3L1, IL12p40, IL-6, IL-8, TNF-α, and IL-1β suggesting a different pathway of immune response in asthma and COPD." (PMID 32842623, 2020). "The phase 2b PATHWAY study demonstrated that blocking TSLP with tezepelumab may be an effective strategy for the treatment of severe, uncontrolled asthma, with reductions in exacerbations observed irrespective of baseline inflammation status." (PMID 33050934, 2020). "Obesity did not influence TSLP and IL-33 mRNA expression in any of the evaluated groups, but BMI might impact the IL-17A mRNA expression in asthma." (PMID 32842623, 2020). "The serum OX40L level showed a significant positive correlation with serum IgE, blood percentages of eosinophils and neutrophils, serum IL-6 and TSLP, and showed a negative correlation with asthma control test (ACT) score and forced expiratory volume in first second (FEV1%)." (PMID 30890137, 2019).
asthma (continued). "Indeed, in a murine asthma model, it was shown that IL1α release by pulmonary epithelial cells induces allergic sensitization to inhaled house dust mite via autocrine release of Th2-driving cytokines IL25, IL33, and TSLP." (PMID 31427886, 2019). "Therefore, OX40-OX40L constitute an important therapeutic target of asthma, and blockade of OX40L could disrupt TSLP-driven helper type 2 cells-related airway inflammation, thus diminish severe allergic symptoms." (PMID 30890137, 2019). "Overall, these results may suggest that targeting TSLP during early-life RSV infection, especially in male infants hospitalized with severe disease, may limit these changes and may decrease the incidence of childhood asthma." (PMID 31076663, 2019). "Furthermore, we found no deletions or duplications nominally associated with asthma symptoms in loci consistently associated with the disease in previous studies, including: DENND1B, IL1RL1, PDE4D, TSLP, IL13, HLA-DR/DQ and IL33 regions." (PMID 30262839, 2018). "If TSLP plays a similar crucial role in the sensitization in humans, a well-directed intervention against this cytokine will be a promising approach for preventive asthma therapy; however, no clinical studies have been initiated yet." (PMID 31826038, 2018). "In the instance of asthma, there is an aberrant response to non-parasite triggers such as allergens, viruses, or mucosal injury leading to epithelial cells producing cytokines, including IL-25, IL-33, thymic stromal lymphopoietin (TSLP), and IL-1α." (PMID 29034234, 2017). "Recent studies have found that cytokine alarmins, including thymic stromal lymphopoietin (TSLP), IL-25, and IL-33, produced by epithelial cells and some hematopoietic cells play important roles in the promotion of TH2 cell development and the initiation of asthma pathogenesis." (PMID 27378934, 2016). "The expression of TSLP observed in biopsy samples was found to be significantly elevated in the polyp tissue of all patient subgroups in comparison with HCs (CRSwNP without asthma) (72.41 ± 53.64, p = 0.048); asthmatics with CRSwNP (104.49 ± 76.78, p = 0.009); and N-ERD (121.23 ± 145.03, p = 0.009)." (PMID 39940994, 2025). "Similarly, TSLP blood expression also exhibited significant differences when comparing the control group with patients (p < 0.001) and with all patient subgroups (CRSwNP without asthma: p < 0.001, N-ERD: p = 0.001, and asthmatics with CRSwNP: p = 0.041)." (PMID 39940994, 2025). "Of particular significance is the potential for eosinophils and FeNO to serve as biomarkers of IL-5, IL-4Ra, or TSLP-driven inflammation, as these cytokines may constitute targets for future biological therapies, regardless of the co-existence of asthma or COPD." (PMID 40589741, 2025). "In addition, TSLP is also thought to play an important role in the early stages of the non‐Th‐2 pathway, making it a potential target for addressing the unmet need of patients with non‐eosinophilic, nonallergic asthma." (PMID 39267467, 2024). "Finally, we must recall here that, among the previously cited molecules, the results of the NAVIGATOR trial on the use of tezepelumab (an antibody against TSLP) are promising for both asthma and CRSwNP, even though this drug is not at present approved for treating the latter condition." (PMID 39595211, 2024). "Furthermore, ILC2s in bronchoalveolar lavage fluid with high levels of TSLP were found to be steroid-resistant, suggesting that the TSLP/ILC2 axis is an important therapeutic target that is not responsive to inhaled corticosteroids, the gold standard in asthma therapy." (PMID 38672419, 2024). "Additionally, there was no observed increase in TSLP concentrations during asthma exacerbations." (PMID 38731070, 2024). "In addition to driving type 2 and non-type 2 inflammation, TSLP expression is increased in airway smooth muscle in asthma and may play a role in the interactions between airway smooth muscle and mast cells." (PMID 39588080, 2024).
asthma (continued). "The question is whether TSLP can be a cytokine of interest in non-severe asthma as well." (PMID 38731070, 2024). "However, the unique action of tezepelumab-ekko on TSLP—an upstream regulator of multiple inflammatory pathways—suggests a broad potential application in severe asthma, particularly in phenotypes not adequately controlled by current biologic therapies targeting more downstream molecules." (PMID 38525773, 2024). "Moreover, TSLP could be a cytokine of interest also in non-severe asthma according to a recent study assessing plasma TSLP in asthmatic adults." (PMID 37628907, 2023). "Indeed, regardless of their atopic status or the viral etiology, infants with nasal TSLP production were more likely to receive maintenance asthma treatment, including the combination of montelukast plus IGC, usually indicated for higher severity levels of asthma." (PMID 36694181, 2023). "Finally, SNPs that were molecular QTLs in our study colocalized with asthma GWAS SNPs, revealing 46 unique colocalizations that included both known asthma loci (e.g., 17q12-21 and TSLP) and loci that did not meet stringent criteria for genome-wide significance in the GWASs (e.g., IRF5 and PMM1)." (PMID 34629083, 2021). "The specific cellular source of cytokine production in asthma is unclear, although evidence shows that allergens, including HDM, may activate airway epithelium leading to the release of mediators including IL-25, IL-33, and thymic stromal lymphopoietin, which activate ILC2." (PMID 30122959, 2018). "Importantly, TSLP has been shown to be upregulated in human airway epithelial cells upon infection with respiratory viruses, such as rhinovirus (RV), respiratory syncytial virus (RSV) and hMPV, providing a possible link between viral infections and asthma pathogenesis." (PMID 29343779, 2018). "Thus, based on these genetic findings, we can postulate that TSLP antagonists (but not agonists) might improve asthma symptoms." (PMID 29333270, 2017). "Tezepelumab, the first biologic targeting TSLP, was approved by the FDA in 2021 for the add-on maintenance treatment of severe asthma, regardless of phenotype or endotype." (PMID 40236701, 2025). "Mice in group B administered with TSLP/OVA showed increased serum IgE levels (albeit not statistically significant) when compared to mice in group A without the TSLP/OVA challenge, confirming the successful establishment of the asthma model." (PMID 41294800, 2025). "Other biologics targeting type 2 immunity, such as anti-IL-4Rα (targeting both IL-4 and IL-13, dupilumab) or anti-TSLP (tezepelumab), are to date in phase II or III trials in type-2- and non-type-2-immunity-driven asthma." (PMID 32296705, 2020). "Other important markers which are frequently studied in asthma and COPD such as periostin, eotaxin and TSLP, though not significant, exhibited an altered profile in ACO." (PMID 32448302, 2020). "We performed an in‐depth appraisal of indirect head‐to‐head comparisons of biologics approved for asthma, including anti‐IL5/5Rα (mepolizumab, benralizumab), anti‐IL4Rα (dupilumab), anti‐TSLP (tezepelumab) and anti‐IgE (omalizumab), which was neither a systematic review nor a meta‐analysis." (PMID 40156481, 2025). "LTRAs alone might increase inflammation and exacerbate asthma by inducing the production of IL-25, IL-33, and TSLP; therefore, LTRA monotherapy may not be an appropriate therapeutic option for asthma." (PMID 36674744, 2023). "Similarly, in our mouse experiments, we observed increased RANTES production in an asthma model of MAP3K19−/− mice, whereas the increased TSLP- and TWEAK-expressing cells in the MAP3K19−/− mice were no different from those of the wild type." (PMID 37998736, 2023).
allergic disease (205 papers, 2008 to 2026). An immune response that occurs following re-exposure to an innocuous antigen, and that requires the presence of existing antibodies against that antigen. "Thymic stromal lymphopoietin (TSLP) is known to promote Th2 responses in allergic disease, however, its role in sepsis associated ARDS remains limited." (PMID 40486522, 2025). "Analysis of the TSLP SNP rs2289277 revealed that individuals carrying the risk allele [C] had nearly double the risk of developing allergic diseases, with homozygotes for the [C] allele showing a nearly threefold increased risk for AD, FA, and anaphylaxis." (PMID 39860604, 2025). "The presence of TSLP rs2289277 further increased the risk of having two concurrent allergic diseases, with the highest risk observed in patients with all three conditions, where the risk was sevenfold higher in the codominant model." (PMID 39860604, 2025). "Recent studies found dysregulation of the TSLP–TSLP receptor (TSLPR) pathway is associated with the pathogenesis of not only allergic diseases but also a wide variety of cancers including both solid tumors and hematological tumors." (PMID 38566968, 2024). "Surprisingly, we found unchanged levels of the allergy-associated cytokine TSLP in skin of Spink5 cKO mice, which contradicts previous studies with Spink5-/- mice, showing TSLP up-regulation in keratinocytes through KLK5-mediated PAR-2 activation." (PMID 38316920, 2024). "Nuclear alarmins (TSLP, IL-33, IL-25) appear to have a critical role in IgE-mediated allergies but are also implicated in entities such as eosinophilic esophagitis." (PMID 37048784, 2023). "The epithelial cell–derived danger signal mediators IL-33, TSLP, and IL-25 are consistently associated with type 2 immune responses in allergic diseases." (PMID 36941691, 2023). "TSLP is a member of the IL-2 cytokine family and is associated with allergic diseases such as atopic dermatitis and allergic asthma." (PMID 36674744, 2023). "Genome-wide association studies (GWAS) have shown an association between allergic diseases and genetic polymorphisms in genes such as TSLP, IL33, and IL1RL1, which encode the IL-33 receptor ST2." (PMID 36941691, 2023). "Recent studies, in both humans and mouse models, have implicated thymic stromal lymphopoietin (TSLP) in the development and progression of allergic diseases as one of the cytokines that is involved in driving allergic inflammatory responses." (PMID 36660742, 2022). "The production of TSLP is under genetic control and common variants in TSLP promote susceptibility to allergic diseases including EoE." (PMID 35759448, 2022). "Second, TSLP is reported to be associated with allergy and IgE secretion and IgG4-RD patients are frequently suffered from allergic conditions, and elevated serum IgE are commonly observed in IgG4-RD." (PMID 36076269, 2022). "Although two isoforms (short form and long form) of TSLP have been demonstrated in human tissues, the long form of TSLP (lfTSLP) is strongly implicated in the pathogenesis of allergies and cutaneous immune-mediated diseases." (PMID 34249003, 2021). "For example, allergic diseases, which are often associated with AD, are primarily characterized by increased levels of IL-4, IL-5, IL-13, IL-31, and thymic stromal lymphopoietin (TSLP)." (PMID 32676572, 2020). "While some polymorphisms in or near the TSLP gene have been reported to be associated with multiple allergic diseases, the specific mechanism underlying the involvement of these polymorphisms has yet to be revealed." (PMID 31768185, 2019). "TSLP has been originally implicated in a variety of allergic diseases (e.g., atopic dermatitis, bronchial asthma, eosinophilic esophagitis)." (PMID 30057581, 2018). "TSLP is another epithelial cytokine implicated in pathogenesis of allergic diseases that directs DCs towards Th2 responses and links epithelial cell activation to dendritic cell mediated immune regulation." (PMID 28198394, 2017).
allergic disease (continued). "Although the importance of TSLP in the pathogenesis of allergic diseases is widely recognised, little is currently known about the direct interplay between TSLP, filaggrin-deficient skin and naïve CD4+ T cells in humans." (PMID 28377574, 2017). "In total, 3 of 5 Barrier-deficient, 2 of 2 3D, and 1 of 9 Epidermal dynamic loci within the TSLP TAD were associated with at least one allergy-associated SNP." (PMID 28953906, 2017). "The SNP was however associated with a DNA methylation signature in whole blood that was also associated with a SNP previously associated with allergy, and with expression of the cytokine TSLP in blood." (PMID 27149122, 2016). "We further observed association of the genetic variant with a DNA methylation signature in blood that in turn is associated with allergy and expression of the gene TSLP (Thymic stromal lymphoprotein) in blood." (PMID 27149122, 2016). "It has been shown that a TSLP deficiency can attenuate allergic reactions by the down-regulation of STAT6 in mast cells." (PMID 27863430, 2016). "The role of mast cells during TSLP-mediated responses further extenuates the TSLP associated responses during allergy." (PMID 23437132, 2013). "Association studies of allergy related phenotypes using genetic polymorphisms have been performed in different populations; with some recent studies showing possible roles of human genetic polymorphisms of the TSLP gene in allergic diseases." (PMID 22973903, 2012). "Thymic stromal lymphopoietin (TSLP) is an epithelial cell-derived cytokine, implicated in the development and progression of allergic diseases." (PMID 22973903, 2012). "In the present study, we selected the representative tag SNPs in and near the TSLP gene region and the SNPs confirmed to be the candidate locus associated with allergy in previous studies." (PMID 22973903, 2012). "The alarmins, IL-25, IL-33, and TSLP activate ILC2s and are linked to allergic diseases." (PMID 41915169, 2026). "The analysis of the TSLP SNP rs2289277 polymorphism revealed a significant association between the risk C allele and increased susceptibility to specific allergic diseases, such as AD, FA, and anaphylaxis, with a higher risk in homozygous CC compared to the allele model." (PMID 39860604, 2025). "Carrying a higher number of the risk allele (C) in the TSLP SNP rs2289277 is associated with the greatest likelihood of having multiple concurrent allergic diseases, with the highest risk observed in individuals with all three conditions—AD, AF, and anaphylaxis—simultaneously." (PMID 39860604, 2025). "TSLP, mostly expressed by epithelial cells, is considered a Th2-promoting master switch implicated in Th2-dominated pathologies in the skin, lung and other organs, and is therefore a focus in allergy-related research." (PMID 33429916, 2021). "Cells that respond to TSLP and IL-33 include T-lymphocytes, type 2 innate lymphoid cells, eosinophils, neutrophils, basophils and mast cells, many of which are often associated with type 2 immune responses, such as allergies." (PMID 31275312, 2019). "Epithelial cell-derived TSLP mediates chemotactic activity in dendritic cells and airway smooth muscle cells, which may be associated with the development of allergy." (PMID 27826297, 2016). "In addition, different studies have shown an association between genetic polymorphisms in the human IL-7Rα chain and TSLP genes with allergy, allergic rhinitis, and bronchial asthma further highlighting a possible link between these proteins and allergy." (PMID 24204367, 2013). "Thus, IL-33, IL-25 and TSLP are considered to be involved in host defense against nematodes and development of Th2-associated disorders, such as allergy." (PMID 24205109, 2013).